TIMM23B (translocase of inner mitochondrial membrane 23 homolog B)
Description:
May participate in the translocation of transit peptide-containing proteins across the mitochondrial inner membrane. the PAM complex (By similarity).
Synonyms: bA592B15.7
Tractability: Antibody: UniProt predicts a signal peptide or a membrane-spanning region. PROTAC: ubiquitination databases record sites on it.
Gene: Protein-coding gene on chromosome 10 (49,942,049 to 49,977,625, forward strand). Ensembl gene ENSG00000204152.
Subcellular location: Mitochondrion inner membrane
Gene Ontology:
Molecular function: protein transmembrane transporter activity; transmembrane transporter activity
Biological process: protein import into mitochondrial matrix
Cellular component: mitochondrion; TIM23 mitochondrial import inner membrane translocase complex; mitochondrial inner membrane
Genetic constraint (gnomAD): Loss-of-function variants: 19 observed, 22.15 expected, observed/expected ratio (o/e) 0.86, 90% interval 0.6 to 1.26. The upper end of that interval is the gene's LOEUF score, 1.26, which puts it in group 5 of 6, group 1 being the genes least tolerant of losing a copy. Missense variants: 182 observed, 204.64 expected, observed/expected ratio (o/e) 0.89, 90% interval 0.79 to 1.01. Synonymous variants: 60 observed, 74.91 expected, observed/expected ratio (o/e) 0.8, 90% interval 0.65 to 0.99.
Homologues: Orthologues: chimpanzee TIMM23 (88% identical), macaque TIMM23 (88% identical), mouse Timm23 (85% identical), rat Timm23-ps8 (84% identical), rat Timm23b (81% identical), tropical clawed frog timm23 (77% identical), rat Timm23 (76% identical), zebrafish timm23b (68% identical), zebrafish timm23a (68% identical), Drosophila melanogaster Tim23 (37% identical), Caenorhabditis elegans timm-23 (7% identical). Paralogues in human: TIMM23 (88% identical).